MYCN (MYCN proto-oncogene, bHLH transcription factor)
Diseases named in the same sentence as MYCN in open-access papers (continued):
Sharing a sentence is not in itself a finding about the gene and the disease.
neuroblastoma (continued). "For instance, transplantation of miR-15a‐, miR‐15b‐ and miR‐16‐expressing neuroblastoma cells into extremely immunodeficient mice has suppressed formation of tumors as well as expression of MYCN, suggesting that these miRNAs have a tumor suppressor role in neuroblastoma through targeting MYCN." (PMID 36348403, 2022). "Conversely, MYCN knockdown triggers cell cycle arrest in MYCN-amplified neuroblastoma cell lines." (PMID 36077650, 2022). "While the role of FGFR2 in neuroblastoma drug resistance and pathogenesis remains to be clarified, our analysis, combined with its function downstream of MYCN, suggests FGFR2 may be an effective target for highly potent small molecule inhibitors." (PMID 34716856, 2022). "Since MYCN and C-MYC belong to a same family, we were wondering if the inhibition of mitochondrial function by VLX600 could also reduce the protein level of MYCN in MYCN-amplified neuroblastoma cells." (PMID 35805002, 2022). "MYCN-amplified neuroblastoma cells showed an elevated ATP demand, indicating that MYCN-amplified cells could be more dependent on functional mitochondria, thus leading to a limited toleration to mitochondrial inhibition." (PMID 35805002, 2022). "Taken together, transsulfuration supplies cysteine for both protein and GSH synthesis in adrenergic MYCN-amplified neuroblastoma cells but prioritizes cysteine for protein synthesis at the expense of GSH and redox balance when cystine uptake is limited, thus triggering ferroptosis." (PMID 35484422, 2022). "It was soon discovered that MYCN amplification predicts poor prognosis in neuroblastoma patients." (PMID 36077650, 2022). "Human MYCN is an oncogene amplified in neuroblastoma and many other tumors." (PMID 34625907, 2022). "Moreover, several genes involved in DNA repair are known to be deregulated in MYCN-amplified neuroblastomas." (PMID 36445966, 2022). "Moreover, we observed a downregulated pattern for the expression of at least a subset of these genes in MYCN-amplified neuroblastoma compared with MYCN-silent neuroblastoma." (PMID 36245757, 2022). "In neuroblastoma, MYCN gene amplification is related to the poor prognosis of patients." (PMID 35992200, 2022). "Additional individual analysis of the expression pattern of key oncogenic TFs verified this clear trend of elevated expression among the transcriptomes of the MYCN-amplified compared to the non-MYCN-amplified neuroblastoma cell lines (center and right, dot plots)." (PMID 36139535, 2022). "And a somewhat unphysiological result comes from a mouse model of neuroblastoma, created by expressing high levels of human MYCN in neuroectoderm: here, additional expression of NYCM did not increase number of tumors, but did increase the number of distant metastases." (PMID 35451603, 2022). "In conclusion, neuroblastoma cells with high MYCN levels were more sensitive to both aryl sulfonamides suggesting that this oncogenic subtype of tumours may respond well to these compounds in a clinical setting." (PMID 35296644, 2022). "MYC is the most broadly deregulated oncogene in a wide range of malignant tumors, whereas MYCN is frequently amplified in neural tumors such as neuroblastoma and small cell lung carcinoma, and MYCL amplifications are solely reported in small cell lung carcinoma." (PMID 35013218, 2022). "Thus, MYCN oncogene amplification is the most important genomic feature in neuroblastoma for classification and staging." (PMID 35890083, 2022). "We tested the association between germline telomere length and the following 10 important clinical characteristics in neuroblastoma: sex, age at diagnosis, primary site, tumor stage, tumor differentiation, MYCN amplification, 1p deletion, 11q deletion, 17q gain, and risk group." (PMID 35902621, 2022).
neuroblastoma (continued). "Also in other tumor entities, false-positive ALK expression has been reported, e.g., in neuroblastoma mediated by MYCN amplification." (PMID 35756632, 2022). "MYCN-amplification can cause several negative events in the tumor microenvironment and inflammatory regulation of neuroblastoma, such as damage to the infiltration and activation of T cells, more vascularized tumor, and downregulation of MHC I." (PMID 35578692, 2022). "Interestingly, AHCY knockout or medicine-mediated suppression caused an elevation in programmed cell death, particularly in MYCN-magnified neuroblastoma cells." (PMID 36211359, 2022). "Transcriptional activation of the mevalonate pathway is also observed in human high-risk neuroblastoma in comparison with low-risk tumors, which is independent of the MYCN amplification status." (PMID 36077650, 2022). "Therefore, the use of system Xc− selective inhibitors or TFR1 agonists to treat MYCN-amplified neuroblastoma will increase the level of lipid peroxidation and eventually lead to ferroptosis of tumor cells." (PMID 35530363, 2022). "We could show that miR-548l found within the 11q region is downregulated in neuroblastoma cell lines with 11q deletion or MYCN amplification." (PMID 36396668, 2022). "MYCN has a key role in promoting FAO in MYCN-amplified neuroblastoma cells." (PMID 36077650, 2022). "MYCN has a major role in promoting purine biosynthesis in neuroblastoma cells." (PMID 36077650, 2022). "As well as developmental regulators of neurogenesis, the MYC or MYCN oncogenes play a key role in maintaining the high level of cell growth in neuroblastoma tumours; the proliferation of SH-SY5Y cells is supported by MYC and the proliferation of IMR32 is driven by MYCN." (PMID 36263020, 2022). "The International Neuroblastoma Risk Group (INRG) classification system is currently being used as a consensus approach for pretreatment risk classification by the clinical features, tumor histology and molecular markers, particularly MYCN status." (PMID 35681607, 2022). "We know very little about the metabolic reprogramming in high-risk neuroblastoma tumors that carry no MYCN amplification." (PMID 36077650, 2022). "Knockdown of AHCY in adrenergic high MYCN but not mesenchymal neuroblastoma cells impaired colony formation, which was associated with reduced GSH levels and reduction of GSH reduced-to-oxidized ratios." (PMID 35484422, 2022). "In summary, MYCN is a vital index influencing neuroblastoma prognosis." (PMID 35820898, 2022). "Further studies by the authors suggested that, in MYCN‐high adrenergic neuroblastoma cells, upregulated transsulfuration pathway maintains the source of intracellular cysteine for protein synthesis at the expense of GSH synthesis, thus triggering a ferroptosis vulnerability." (PMID 35908258, 2022). "Most high-risk neuroblastomas exhibit high levels of telomerase activity, which are caused by induction of the telomerase reverse transcriptase (TERT) gene through MYCN over-expression in MYCN-amplified tumors, or through genomic rearrangements of the TERT locus." (PMID 35953764, 2022). "Therefore, BET proteins are the potential therapeutic targets to combat MYCN amplified neuroblastoma by inhibiting the expression of MYCN and other related oncogenes." (PMID 36187481, 2022). "MYCN oncogene amplification is a genetic marker detected in about 20–30% of neuroblastoma patients." (PMID 35820898, 2022). "The MYCN expression levels in this study were of the same magnitude as seen in neuroblastomas." (PMID 35729105, 2022). "Increased TRPM2 in tumors may be both a driver of high FOXM1 and the embryonic stem cell program seen in non-MYCN amplified Stage 4 neuroblastoma patients, contributing to increased metastasis and worse outcome." (PMID 36446940, 2022).
neuroblastoma (continued). "In childhood neuroblastoma, the most important feature appears to be amplification of the MYCN proto-oncogene, which occurs in ~25% of primary tumors and is considered a high-risk aggressive clinical marker correlated with advanced stage disease and treatment failure." (PMID 35805002, 2022). "Additionally, the inhibition of the ALDH18A1- MYCN positive feed back loop attenuates MYCN-amplified neuroblastoma growth." (PMID 36818667, 2022). "MYCN amplification, the de no oncogene driver that accounts for 20% of neuroblastoma, is observed in high-risk neuroblastoma and poor patient survival." (PMID 35664308, 2022). "CCNE1 kinase inhibitors are potential drugs for MYCN-dependent neuroblastoma." (PMID 35655142, 2022). "Overexpression of MYCN mRNA may also have an important role in promoting neuroblastoma (NB) beyond the translation of MYCN protein." (PMID 36505784, 2022). "Moreover, miR-15a-5p blocks neuroblastoma progression by directly targeting v-myc myelocytomatosis viral related oncogene, neuroblastoma derived (avian) (MYCN)." (PMID 35428780, 2022). "Also, T cell receptor analysis showed that MYCN-amplified neuroblastomas had decreased levels of infiltrating lymphocyte signatures compared to non-MYCN-amplified tumors." (PMID 35362827, 2022). "Importantly, blocking fatty acid synthesis through the FASN inhibitor C75 induces cell death only in high-MYCN-expressing cells, indicating a crucial role for fatty acid synthesis in sustaining the survival of MYCN-amplified neuroblastoma cells." (PMID 36077650, 2022). "Previously, SKP2 was determined as a prognostic factor of high risk neuroblastoma independent of MYCN status." (PMID 35764946, 2022). "BET inhibitors target MYCN transcription and show therapeutic efficacy against neuroblastoma." (PMID 36286044, 2022). "The analysis of MYCN-amplified versus MYCN-silent neuroblastoma also showed a significant downregulation of CDKN2C in MYCN-amplified samples, suggesting a potential, general oncogenic function for the lowered expression of CDKN2C for MYCN-amplified pediatric cancers." (PMID 36245757, 2022). "MYCN amplification is detected in approximate 25% neuroblastoma patients." (PMID 35764946, 2022). "TFAP4 knockdown selectively hinders MYCN-elicited neuroblastoma growth both in vitro and in vivo." (PMID 34983307, 2022). "Finally, in mouse tumor models of MYC-driven AML, breast cancer, and MYCN-amplified neuroblastoma, treatment with MYCMI-7 downregulates MYC/MYCN, inhibits tumor growth, and prolongs survival through apoptosis with few side effects." (PMID 36874405, 2022). "MYCN is frequently amplified in several cancer types, most notably in neuroblastoma, where it is well known to enhance cell proliferation and survival; NCYM is co-amplified with it as a result of the genomic architecture of the two genes, and it too is regarded as contributing to oncogenesis." (PMID 35451603, 2022). "Therefore, MYCN is considered a remarkable target for drug development in the treatment of MYCN amplified neuroblastoma." (PMID 36187481, 2022). "MYCN amplification is a genetic cause of neuroblastoma, and it was reported that inhibition of the PI3K-AKT-mTOR signaling pathway could inhibit neuroblastoma growth by destabilizing MYCN." (PMID 36585695, 2022). "Moreover, it was found that high HNF4A-AS1 expression is associated with MYCN amplification in neuroblastoma tumors and that MYCN overexpression or knockdown in neuroblastoma cell lines increases or downregulates HNF4A-AS1 expression, respectively." (PMID 36077650, 2022). "Moreover, IHC staining of serial sections from an unfavorable histology MYCN amplified neuroblastoma demonstrated that the majority of CD68+ macrophages co-expressed CD163." (PMID 35525858, 2022).
neuroblastoma (continued). "While THZ1 appears to preferentially affect genes controlled by super-enhancers in neuroblastoma, MYCN-dependent genes in particular, there is evidence to indicate that the off-target inhibition of CDK12 and CDK13 rather than of CDK7 is responsible for the transcriptional effects of THZ1." (PMID 35681734, 2022). "In a recent study of the super-enhancer landscapes in primary neuroblastoma patient samples, the presence of these 2 states was confirmed, and the ADRN phenotype was found to comprise 3 distinct subtypes: MYCN-amplified, non–MYCN-amplified high-risk, and non–MYCN-amplified low-risk signatures." (PMID 35943801, 2022). "Inhibition of MDM2 suppresses the progression of MYCN-dependent neuroblastoma." (PMID 35655142, 2022). "Complete tumour regression without relapse was observed in both xenograft and the Th-MYCN transgenic model of neuroblastoma after indisulam treatment, with RBM39 loss, RNA splicing and metabolic changes confirmed in vivo." (PMID 35296644, 2022). "Five patients were stratified into intermediate-risk group and 41 were categorized into high-risk group at initial diagnosis on the basis of the following factors: stage, age, International Neuroblastoma Pathologic Classification, amplification of the MYCN oncogene within tumor tissue." (PMID 35359419, 2022). "Both MYCN-amplified and non-MYCN neuroblastoma cell lines are sensitive to statins, suggesting that statins are potential therapeutics for high-risk neuroblastoma." (PMID 36077650, 2022). "The MYCN oncogene has great potential to induce the development of more aggressive neuroblastomas." (PMID 36286044, 2022). "Abrogation of cell death induced by cystine depletion in MYCN‐expressing neuroblastoma cells upon treatment with ferroptosis inhibitors or iron chelators further support their hypothesis that MYCN regulates ferroptosis." (PMID 35908258, 2022). "Thus, this proves that MYCN amplification is a strong prognostic factor for the outcome in patients with neuroblastoma." (PMID 36360435, 2022). "Moreover, we evaluated each compound against two neuroblastoma cell lines that were different in many aspects, more specifically by their expression of the efflux pump P-gp and the MYCN gene amplification." (PMID 35890083, 2022). "SUVmax has been reported to correlate with MYCN amplification and may serve as a prognostic biomarker in neuroblastoma." (PMID 36353561, 2022). "We found that MYCN downregulation by siRNA leads to neuroblastoma differentiation as measured by morphological changes and NF-L-expressing neurite outgrowth, which may indicate that differentiated cells should have lower MYCN levels." (PMID 34522028, 2022). "The combination of IHC and FISH to determine MYCN stability could potentially be of greater importance as prognostic indicators for patients diagnosed with neuroblastoma compared to singular factors." (PMID 35820898, 2022). "MYCN amplification is an established marker of poor prognosis in neuroblastoma." (PMID 36319669, 2022). "IONP–GA/PAA significantly killed glioblastoma (U87MG and U373MG), high-risk MYCN amplified neuroblastoma (IMR32), fibrosarcoma (HT1080), and HT22 neuronal (non-tumorigenic) cell lines." (PMID 35807217, 2022). "Recent studies highlighted the role of iron in MYCN-dependent neuroblastoma and ferroptosis." (PMID 35484422, 2022). "Interestingly, the modern CT-based approach has shown the ability to predict MYCN amplification (MNA) status in neuroblastoma through the generation of radiomics profiles of tumors, highlighting the great potential of this technique." (PMID 36139583, 2022). "Furthermore, several promoter genes including their core regulatory circuitries (CRCs) have been identified for neuroblastoma, such as MYCN, ALK and TERT." (PMID 35328549, 2022). "MYC overexpression is seen in a number of high-risk neuroblastoma patients (~10%) without MYCN amplification." (PMID 36185250, 2022).
neuroblastoma (continued). "The natural lead compounds identified through the modern CADD approaches will be able to reduce the overexpression of the BET protein and, subsequently, the overexpression of MYCN proto-oncogene, resulting in hindering the activity of the neuroblastoma and related disease." (PMID 36286044, 2022). "C-MYC upregulation has been reported to enhance mitochondrial activity in various tumors; since MYCN and C-MYC belong to the same gene family, we speculated that mitochondrial activity could be as well strengthened in MYCN-amplified neuroblastoma cells." (PMID 35805002, 2022). "MYCN amplification (MNA) has been proved to be related to poor prognosis in neuroblastoma (NBL), but the MYCN-related immune signatures and genes remain unclear." (PMID 36419120, 2022). "These cell line studies suggest a unique MYCN‐dependent metabolic rewiring that might create a new vulnerability for therapeutically targeting in MYCN‐high adrenergic neuroblastomas." (PMID 35908258, 2022). "In contrast to serine-glycine synthesis, increased activation of the mevalonate pathway is observed in high-risk neuroblastoma tumors, independent of the MYCN amplification status." (PMID 36077650, 2022). "Furthermore, because MYCN amplification is also a common somatic event in neuroblastoma, we examined the behavior of the signature genes in a public data set derived from 88 neuroblastoma tumors, with 16 harboring a MYCN amplification." (PMID 36245757, 2022). "Pharmacologically inhibition of the protein potently depletes MYCN in neuroblastoma cells." (PMID 36286044, 2022). "In addition to promoting glutamine uptake, MYCN activates glutaminolysis in neuroblastoma cells, which is a process of replenishing the TCA cycle by converting glutamine to α-ketoglutarate." (PMID 36077650, 2022). "A subset of neuroblastoma is characterised by genomic amplification of the MYCN oncogene." (PMID 35711922, 2022). "Moreover, SLC7A5 or SLC43A1 depletion reduces MYCN expression by interfering with MYCN mRNA translation and attenuates neuroblastoma cell growth in vitro and in vivo." (PMID 36077650, 2022). "Indeed, ferrostatin-1 (Fer-1), a specific inhibitor of ferroptosis, or a lipophilic antioxidant or an intracellular iron chelator such as ciclopirox olamine (CPX) averted death in cystine-deprived high MYCN neuroblastoma cells." (PMID 35484422, 2022). "Therefore, we combined mTOR activity, differentiation score, and MYCN status into a single score to predict the survival of neuroblastoma patients." (PMID 35490242, 2022). "MYCN nonamplified paediatric neuroblastoma patients with higher risk points had significantly shortened overall survival." (PMID 35655142, 2022). "In MYCN-amplified neuroblastoma cells, this effect may be induced by downregulation of MYCN transcription, defects in DNA repair, accumulation of DNA damage, and apoptosis." (PMID 36227363, 2022). "Depletion of EZH2 expression in multiple MYCN-amplified and -nonamplified neuroblastoma cells by specific sgRNAs or shRNAs caused minimal changes in MYCN mRNA levels." (PMID 35013218, 2022). "In neuroblastoma, frequency of inactivation is correlated with aggressive disease behavior: hemizygous deletion has been detected in 18% of early-stage tumors, in 55% of patients with stage 3 and 4 disease, and in 84% of MYCN-amplified tumors." (PMID 35768791, 2022). "Similarly with E2F1, E2F3 was also additively predicted the clinical overall survival of neuroblastoma with MYCN amplification or age of diagnosis." (PMID 35764946, 2022). "Moreover, MYCN amplification induced E2F5 expression to promote neuroblastoma progression through regulation of cell cycle pathway." (PMID 35764946, 2022). "The authors chose childhood neuroblastoma as a model to study MYCN‐driven cancers." (PMID 35908258, 2022).